PDZD4 (PDZ domain containing 4)
Synonyms: KIAA1444; PDZK4; PDZRN4L; LU1; FLJ34125; LNX5
Tractability: PROTAC: ubiquitination databases record sites on it; its protein half-life has been measured.
Gene: Protein-coding gene on chromosome X (153,802,166 to 153,830,930, reverse strand). Ensembl gene ENSG00000067840.
Subcellular location: Cytoplasm, cell cortex
Gene Ontology:
Cellular component: cell cortex
Homologues: Orthologues: chimpanzee PDZD4 (99% identical), macaque PDZD4 (99% identical), mouse Pdzd4 (93% identical), rat Pdzd4 (93% identical), rabbit PDZD4 (93% identical), dog PDZD4 (93% identical), guinea pig PDZD4 (92% identical), pig PDZD4 (91% identical), tropical clawed frog pdzd4 (72% identical), zebrafish PDZD4 (54% identical), zebrafish PDZD4 (51% identical), Drosophila melanogaster Slip1 (22% identical), and 1 more. Paralogues in human: PDZRN3 (50% identical), PDZRN4 (48% identical).
Diseases named in the same sentence as PDZD4 in open-access papers:
PDZD4 is named in the same sentence as 15 diseases in open-access papers, as found by Europe PMC text mining. Sharing a sentence is not in itself a finding about the gene and the disease. The quoted sentences say what the papers report.
synovial sarcoma (4 papers, 2010 to 2022). "PDZD4 is up-regulated in synovial sarcomas, and high expression of PDZD4 promotes the proliferation capacity of synovial sarcomas cells." (PMID 34676211, 2021). "For example, the PDZD4 gene was reported to be upregulated in 13 of 13 synovial sarcomas (SS), whereas siRNA against PDZD4 resulted in suppression of SS tumor cell growth." (PMID 20806066, 2010).
schizophrenia (2 papers, 2024 to 2025). A major psychotic disorder characterized by abnormalities in the perception or expression of reality. "Also, in a 285 person cohort with autism spectrum disorder (ASD) or schizophrenia, a male with ASD was found to have a significant PDZD4 missense mutation." (PMID 40662097, 2025).
diabetic neuropathy (1 paper, 2025). A chronic, pathological complication associated with diabetes mellitus, where nerve damages are incurred due to diabetic microvascular injury involving small blood vessels that supply these nerves, resulting in peripheral and/or autonomic nerve dysfunction. "In addition, further research is needed to explore the roles of specific biomolecules implicated in diabetic neuropathy development, such as SLC30A1, TRBJ2‐7, OLFM1, TCF7L2, MCF2L, CEP295NL, CEACAM22P, TSHZ2, and PDZD4." (PMID 40692573, 2025).
epilepsy (1 paper, 2026). A brain disorder characterized by episodes of abnormally increased neuronal discharge resulting in transient episodes of sensory or motor neurological dysfunction, or psychic dysfunction. "FRMPD4 (FERM and PDZ Domain Containing 4) has previously been associated with intellectual disability and epilepsy." (PMID 41959831, 2026).
gastric cancer (1 paper, 2023). A primary or metastatic malignant neoplasm involving the stomach. "When the eight characteristic genes (ENTPD3, PDZD4, CNN1, GTPBP4, FPGS, UTP25, CENPW, and FAM111A) are all fitted into one variable, the AUC of the ROC curve is 0.996, indicating a good diagnostic efficiency for gastric cancer." (PMID 37007099, 2023). "We have established the early diagnosis model of eight characteristic genes (ENTPD3, PDZD4, CNN1, GTPBP4, FPGS, UTP25, CENPW, and FAM111A) for gastric cancer." (PMID 37007099, 2023).
tumor (8 papers, 2010 to 2023). "It was worth mentioning that five of them were downregulated in tumor samples, including DLAT, MTF1, PDZD4, FDX1, and RPS25, and the rest of the genes were all upregulated." (PMID 36010978, 2022).
cancer (1 paper, 2017). A tumor composed of atypical neoplastic, often pleomorphic cells that invade other tissues.
PDZD4 also shares sentences with these, for which no sentence is quoted: adenocarcinoma (1 paper); autism spectrum disorder (1); breast carcinoma (1); colon cancer (1); coronary heart disease (1); infection (1); Intellectual disability (1); lung carcinoma (1).